IFIT3 (interferon induced protein with tetratricopeptide repeats 3)
Diseases named in the same sentence as IFIT3 in open-access papers (continued):
Sharing a sentence is not in itself a finding about the gene and the disease.
melanoma (7 papers, 2017 to 2026). A malignant, usually aggressive tumor composed of atypical, neoplastic melanocytes. "Genetic defects in IFIT3 have also been suggested to confer resistance to immunotherapy in melanoma." (PMID 40564154, 2025). "In melanoma patients treated with anti-PD1 and cetirizine combination therapy, upregulations of IFI27, IFIT1, and IFIT3 are associated with M1 polarization of macrophages and improved patient outcome." (PMID 37174688, 2023). "Conversely, overexpressing IFIT1, IFIT2 and IFIT3 in human melanoma cell lines enhanced the sensitivity of human melanoma cell lines to T-cell killing, thereby recapitulating the effects of ganetespib treatment." (PMID 28878208, 2017). "In SKCM, low expression levels of IFIT3, similar to IFIT1 and IFIT2, have been found to be correlated with patients’ poor overall survival and DSS and decreased sensitivity of melanoma cells to dasatinib and T-cell killing and apoptosis." (PMID 40564154, 2025). "Various studies suggest that IFIT3 might serve as a clinical biomarker in OSCC, lung cancer, gastrointestinal tract and hematological malignancies, melanoma, breast, bladder and thyroid and other cancers." (PMID 40564154, 2025). "For instance, RNA-seq analysis of human melanoma COLO829 cells transfected with MITF short hairpin RNA (shRNA) demonstrates an up-regulation of over 17 of the same 55 innate immune DEGs identified in Mitfmi-vga9/+ McSCs, including Ifih1, Ifit3, Irf7, Parp9, and Stat1 (GSE50686)." (PMID 29723194, 2018). "Upregulation of interferon response genes in multiple melanoma cell lines by ganetespib was confirmed by quantitative real time PCR and Western blot analyses, most strongly for members of the IFN-induced protein with tetratricopeptide repeats (IFIT) gene family: IFIT1, IFIT2 and IFIT3." (PMID 28878208, 2017). "Melanoma patients lacking clinical responses to the anti-CTLA-4 immunotherapeutic, ipilimumab (as compared to those who had such responses) harbored a much higher rate of genomic defects in the IFN-γ pathway genes, including genetic losses of IFIT1, IFIT2 and IFIT3." (PMID 40564154, 2025).
pancreatic ductal adenocarcinoma (7 papers, 2018 to 2025). An infiltrating adenocarcinoma that arises from the epithelial cells of the pancreas. "However, a previous study found that high IFIT3 expression could enhance the chemotherapeutic resistance of pancreatic ductal adenocarcinoma (PDAC) cells and was independently associated with the poor survival of PDAC patients." (PMID 31949544, 2019). "Interferon-induced protein with tetratricopeptide repeats 3 (IFIT3) is an interferon-stimulated through JAK/STAT signaling pathway during pancreatic ductal adenocarcinoma (PDAC)." (PMID 34421635, 2021). "As described by Zhao and co-authors, elevated expression of IFIT3 enhanced anti- apoptotic activity and chemotherapy resistance in pancreatic ductal adenocarcinoma." (PMID 29986702, 2018). "AND IFIT3 may also contribute to chemotherapy resistance in pancreatic ductal adenocarcinoma, with transcriptomic analysis revealing enriched pathways in high IFIT3 groups, such as inflammation, immune response, NF-κB signaling, and apoptosis." (PMID 40463715, 2025). "In pancreatic ductal carcinoma (PDAC), IFIT3 expression was proposed to be a prognostic marker of PDAC, as well as shown to mediate antiapoptotic activity and chemoresistance of PDAC cells." (PMID 34622927, 2021).
ZIKV infection (7 papers, 2017 to 2025). "The results showed that ZIKV infection significantly increased OAS2, IFIT3 and IFITM1 levels, and decreased Clorf27, DLG1 and EHBP1 levels." (PMID 32276512, 2020). "Interferon-stimulated genes (ISG) such as MX2, IFIT1, IFIT3, IFITM1, IFI35, and RSAD2 (Viperin) were significantly upregulated after ZIKV infection." (PMID 30781519, 2019). "These included MX1, IFIT1, ISG15, SAMHD1, IFIT3, and STAT1, all of which have been shown to be similarly upregulated by ZIKV infection in other human cell types, including fibroblasts and pluripotent stem cell (iPSC)-derived neural progenitor cells (NPC), as also demonstrated by LC-MS/MS analysis." (PMID 34079533, 2021). "During ZIKV infection we observed a reduction of IFNL1, IFIT1, and IFIT2, but not IFNB, IFIT3, and ISG15 transcription in the absence of DNA-PKcs." (PMID 36311766, 2022).
acute promyelocytic leukemia (6 papers, 2013 to 2025). An aggressive form of acute myeloid leukemia (AML), characterized by arrest of leukocyte differentiation at the promyelocyte stage, due to a specific chromosomal translocation t(15;17) in myeloid cells. "Specifically, IFIT3, also known as ISG60, IFIT4, or retinoic acid inducible gene (RIG-G), was first identified in the acute promyelocytic leukemia cell line NB4." (PMID 34622927, 2021). "IFIT3 was first identified as an all-trans-retinoic acid- and IFN-induced gene in acute promyelocytic leukemia cells." (PMID 24223959, 2013).
dengue virus infection (6 papers, 2013 to 2024). "Additionally, suggestive evidence points towards the antiviral role of IFIT3 in dengue virus infection, as a deficiency in IFIT3 is associated with increased viral production in human lung epithelial cells." (PMID 39664492, 2024). "Previous study suggested that upregulation of IFIT3 plays a protective role in lung epithelial cells in dengue virus infection by an inhibition of apoptosis." (PMID 34075171, 2021). "Dengue virus infection in lung epithelial cells upregulated the Ifit3 gene, which suppressed the virus production." (PMID 29163367, 2017). "Both NME1 and IFIT3 were expressed by CD4+ T cells from dengue-infected patients." (PMID 31624246, 2019).
HIV-1 infection (6 papers, 2014 to 2025). The type species of lentivirus and the etiologic agent of acquired immunodeficiency syndrome (AIDS). "The upregulation of IFIT3 in response to HIV-1 infection and subsequent reduction after cART treatment demonstrated the ability of cART to normalize immune function and reduce chronic immune activation, a key factor in HIV-associated neuroinflammation." (PMID 40936921, 2025). "In primary myeloid cells, both HIV-1 infection and the viral accessory protein Vpr have been shown to activate this pathway, resulting in increased STAT1 phosphorylation together with coordinated induction of ISG15, MX1, IFIT3/IFI44L, and OAS genes." (PMID 41226717, 2025). "We also noted that HIV-1 infection induces a prominent antiviral state in early/mid-gestation HCs, characterized by transcription and secretion of IFN-α and significantly elevated transcription of the RLRs, STAT1, STAT5, ISG15, OAS1, IFIT1, IFIT2, IFIT3, and Viperin." (PMID 34432853, 2021).
leukemia (6 papers, 2016 to 2025). A malignant (clonal) hematologic disorder, involving hematopoietic stem cells and characterized by the presence of primitive or atypical myeloid or lymphoid cells in the bone marrow and the blood. "IFIT1 and IFIT3 have been implicated in proptosis induction in myeloma and leukemia cells." (PMID 41048997, 2025). "In another study in myeloma and leukemia, upregulation of IFIT3 in response to the antiparasitic drug clioquinol, was found to be essential in this drug induced pyroptosis in these malignancies." (PMID 40564154, 2025). "IFIT3 expression levels were reported to be reduced in the peripheral blood of patients with various types of leukemia compared to healthy controls, suggesting a tumor suppressor role of this protein in hematological malignancies." (PMID 40564154, 2025). "Gene-profiling experiments showed that treating human leukemia HL-60 cells with Dip G was associated with a remarkable upregulation of STAT1 target gene expression, including IFIT3 and CXCL10." (PMID 28471454, 2017). "Differences in results regarding the role of IFIT3 in hematological malignancies might be explained by differences in study designs, measured outputs and molecular variabilities between various types of leukemias and require further nuanced understanding." (PMID 40564154, 2025). "Additionally, a recent study reported that treatment with 20 μM clioquinol for 24 h induces pyroptosis of leukemia and myeloma cells via up-regulating IFIT1 and IFIT3." (PMID 39899169, 2025).
lung carcinoma (6 papers, 2016 to 2025). "Interestingly, a study found that Rig-G (an alias of IFIT3) expression was often downregulated in lung cancer, and its low levels were strongly associated with poor prognosis." (PMID 40061935, 2025). "IFIT3 is found to be frequently downregulated in lung cancer tissues and cell lines and is correlated with poor prognosis in patients." (PMID 40564154, 2025). "Overexpression of IFIT3 in lung cancer leads to reduced cell proliferation, growth, migration and EMT." (PMID 40564154, 2025). "IFIT3 has also been shown to reduce lung cancer cell proliferation, migration, and epithelial mesenchymal transition." (PMID 34622927, 2021). "In another study, it was shown that IFIT3 overexpression in lung cancer cells was able to exert an anti-tumor activity." (PMID 34622927, 2021). "A mechanism of regulation of IFIT3 by its direct interaction with circular RNA Circ_BBS9 has been identified to lead to tumor suppressive phenotypes modulating ferroptosis and the tumor immune microenvironment in lung cancer." (PMID 40564154, 2025). "In other malignancies, such as hematological malignancies, HCC and lung cancer, it remains controversial whether IFIT3 acts as a pro-oncogene or tumor suppressor." (PMID 40564154, 2025). "Mechanisms of action of IFIT3 in lung cancer appear to be multifaceted." (PMID 40564154, 2025). "Moreover, IFIT3 has been studied for its antiproliferative activity in different types of solid tumors, including, hepatocellular carcinoma and lung cancer." (PMID 34622927, 2021). "Further, to explore the mechanisms of COL8A1 promoted lung cancer development, we found COL8A1 activated EGFR via upregulation of IFIT1 and IFIT3." (PMID 35280763, 2022).
autoimmune disease (5 papers, 2020 to 2024). A disorder resulting from loss of function or tissue destruction of an organ or multiple organs, arising from humoral or cellular immune responses of the individual to their own tissue constituents. "Considering the association of IFIT3/TBK1 with autoimmune diseases, we propose a potential relevance of IFIT3/TBK1 in SSc." (PMID 39305055, 2024). "Several recent studies have demonstrated that IFIT3 is also in the development and advancement of various autoimmune diseases." (PMID 39305055, 2024). "In addition, IFIT3 is differentially expressed in B cells and monocytes in patients with autoimmune diseases, indicating that the IFIT3 gene may be involved in B cell-mediated humoral immunity." (PMID 37007947, 2023). "Both IFI44 and IFIT3 are type I IFN signature genes, which may contribute to the pathogenesis of autoimmune diseases." (PMID 34760904, 2021).
dermatomyositis (5 papers, 2017 to 2025). Dermatomyositis (DM) is a type of idiopathic inflammatory myopathy characterized by evocative skin lesions and symmetrical proximal muscle weakness. "Through bioinformatics analysis, Ifit3 is also identified as a vital gene in pain-related diseases, such as dermatomyositis and degenerative discs." (PMID 41008561, 2025). "As a result, M2 macrophages were positively associated with the expression of IFIT3, OAS3, ISG15, and RSAD2 in patients with inflammatory cardiomyopathy and dermatomyositis, respectively." (PMID 37118825, 2023). "In one study, ISG15, IFIT3, OAS3, and RSAD2 were prominently enriched in the type I IFN signaling pathway, serving as central hub genes associated with myocarditis-related immune processes, suggesting their potential involvement in the mechanism of myocardial injury in dermatomyositis." (PMID 38753730, 2024). "This miRNA appears to regulate genes enriched in type I interferon signaling pathways (IFIT3, OAS3, ISG15, and RSAD2), which correlate with increased M2 macrophage infiltration in both dermatomyositis and myocarditis." (PMID 40433545, 2025).
HCMV infection (5 papers, 2019 to 2025). "HCMV infection led to a moderate induction of MX1, IFIT3, and ISG15, compared to the mock infected cells, as expected." (PMID 37376632, 2023). "Several ISGs, including IFIT1, IFIT2, IFIT3, Mx1, Mx2, CXCL10 and ISG15 were found to be upregulated transcriptionally following HCMV infection independently of type I IFN-initiated JAK-STAT signaling, but dependent on intact IRF3 signaling." (PMID 30871003, 2019). "Studies of HCMV infection in the presence of cycloheximide (CHX) have shown upregulation of IFIT1 (IFI56), IFIT2 (ISG54), IFIT3 (cig49, ISG60), MxA (the protein produced from the Mx1 gene) and ISG15." (PMID 30871003, 2019). "In the context of the HCMV infection, Ashley and colleagues demonstrated that the promoters of several core IRGs, including IFIT1, IFIT3, MX1, and ISG15, are transcriptionally induced by the activation of the transcription factor IRF3 and therefore function independent of the IFN responses." (PMID 36552792, 2022). "Induction of the IFN-independent ISG viperin during HCMV infection is known to be induced by either IRF3 or IRF1, binding directly to its promoter, and this may also be the mechanism of IFIT1, IFIT2, IFIT3, CXCL10, Mx1, Mx2 and ISG15 upregulation." (PMID 30871003, 2019). "In contrast, upon infection with AD169ΔIE1, we observed a 6.3-, 3.5-, and 2.2-fold decrease in IFIT1, Mx1, and IFIT3 enrichment, respectively, which further supports the crucial role played by the IE1 protein in PAD-mediated citrullination during HCMV infection." (PMID 34162877, 2021).
esophageal squamous cell carcinoma (4 papers, 2024 to 2025). Esophageal squamous cell carcinoma (ESCC) is a type of esophageal carcinoma (EC) that can affect any part of the esophagus, but is usually located in the upper or middle third. "IFIT3 has been proposed to be a likely biomarker of tumorigenesis for esophageal squamous cell carcinoma (ESCC)." (PMID 40564154, 2025).
ischemic cardiomyopathy (4 papers, 2021 to 2025). Ischemic cardiomyopathy is a cardiomyopathy in which a weakness in the muscle of the heart due to inadequate oxygen delivery to the myocardium with coronary artery disease being the most common cause. "IFIT3 is a novel biomarker for human ischemic cardiomyopathy that can inhibit the nuclear factor-kappa B (NF-κB) pathway in injured arteries, resulting in the inhibition of endothelial cell proliferation, migration, and re-endothelialization." (PMID 35955709, 2022). "Three interferon stimulated genes (IFIT2, IFIT3 and IFI44L), as well as key pathways, have been identified as potential biomarkers and therapeutic targets for ischemic cardiomyopathy, and their alternations or mutations have been proven to be strongly linked to cardiac disorders." (PMID 34884921, 2021). "IFIT3 may be a potential therapeutic target for ischemic cardiomyopathy, and IFIT1 and IFIT5 are key genes that are used to predict treatment response in patients with microvascular disease in the early stage." (PMID 34753383, 2021).
lung adenocarcinoma (4 papers, 2020 to 2025). A carcinoma that arises from the lung and is characterized by the presence of malignant glandular epithelial cells. "In lung adenocarcinoma, patients’ tumor high infiltration level of IFIT3-positive neutrophils was positively related to the response to immune-targeted therapy and activation of CD8+ T cells." (PMID 40564154, 2025). "Activation of the STAT1/IRF9/IFIT3 axis via FAM210B (family with sequence similarity 210 member B) has been reported to lead to the inhibition of proliferation and migration of lung adenocarcinoma cells." (PMID 40564154, 2025).
atherosclerosis (3 papers, 2021 to 2024). A disease characterized by the build-up of fatty material and calcium deposition in the arterial wall resulting in partial or complete occlusion of the arterial lumen. "IFIH1, IFIT1, IFIT2, IFIT3, ISG15 and OAS3 had similar expression differences to the training set and had good diagnostic abilities for atherosclerosis." (PMID 36437453, 2022). "IFIT3 is a marker of M1 macrophage polarization and is highly upregulated in atherosclerosis and other inflammatory diseases." (PMID 34868310, 2021). "A previous study identified IFIT1, IFIT2, IFIT3, and ISG15 as immune-related hub genes of atherosclerosis." (PMID 38397063, 2024). "Our study identified IFIH1, IFIT1, IFIT2, IFIT3, ISG15 and OAS3 as immune-related hub genes of atherosclerosis." (PMID 36437453, 2022). "IFIT3, IFIT2 and IFIT1 were the top three proteins potentially playing key roles in atherosclerosis." (PMID 36437453, 2022).
Autoimmunity (3 papers, 2008 to 2025). The occurrence of an immune reaction against the organism's own cells or tissues. "Conversely, the AD-A group demonstrated upregulation of several transcripts implicated in tumorigenesis (CAB39), intracellular signaling (CAB39), autoimmunity (IFIT3), and mTOR signaling (DEPTOR)." (PMID 41010010, 2025). "IFIT3, MIDN, and ILR1 belong to pathways associated with interferon regulation or autoimmunity and were identified in the immune response subclusters (C3 and C4.2)." (PMID 35494238, 2022).
glioma (3 papers, 2023 to 2024). A benign or malignant brain and spinal cord tumor that arises from glial cells (astrocytes, oligodendrocytes, ependymal cells). "The IFIT3+ T cells and Treg identified within the three tumor types were preferentially enriched in adult IDH-W gliomas." (PMID 38094301, 2023).
liver cancer (3 papers, 2023 to 2024). An epithelial or non-epithelial malignant neoplasm that arises from the liver. "IFIT3 can enhance the anti-liver cancer effect of IFN-α by binding transcriptional activators STAT1 and STAT2." (PMID 38753689, 2024). "In a large multicenter study, patients with liver cancer were found to have low expression of IFIT1, IFIT2, and IFIT3." (PMID 38129382, 2023).
lymph node metastasis (3 papers, 2024 to 2026). "IFIT3 overexpression is correlated with advanced tumor-node-metastasis stage, lymph node metastasis, and poor prognosis in patients with LUSC and LCLC." (PMID 41850400, 2026). "In addition, IFIT1 and IFIT3 have been reported to promote the lymph node metastasis of HNSC." (PMID 39392128, 2024). "It was interesting to note that IHC analysis showed aberrant up-regulation of IFIT3 in HNSC tissue microarray and positively correlated with advanced clinical tumor stages and lymph node metastasis respectively." (PMID 38273364, 2024).
myeloma (3 papers, 2025). "For example, in multiple myeloma, IFIT3 activation has been linked to repression of MYC proto-oncogene." (PMID 40564154, 2025).
myocarditis (3 papers, 2023 to 2025). Myocarditis is a condition that is characterized by inflammation of the heart muscle (myocardium). "We found M2 macrophages increased in DM and myocarditis compared to the healthy control, associating with the expression of IFIT3, OAS3, ISG15, and RSAD2 in DM and myocarditis positively." (PMID 37118825, 2023). "We finally identified 4 common hub-genes related to the immune process of myocarditis and DM: IFIT3, OAS3, ISG15, and RSAD2." (PMID 37118825, 2023). "The expression levels of IFIT3, OAS3, ISG15, and RSAD2 were verified in myocardial tissue between myocarditis mice and normal control." (PMID 37118825, 2023).
neuroblastoma (3 papers, 2015 to 2025). Neuroblastoma (NB) is the most common solid, extracranial childhood tumor. "Using the SH-SY5Y neuroblastoma cell line and HIV-infected humanized mice, we examined the effects of the cART drugs, HIV Tat protein, and HIV-1 virus on STAT1 and IFIT3 expression." (PMID 40936921, 2025). "In neuroblastoma cells, the poly(I:C) triggered inductions were significantly blunted by PINK1 knockdown for RSAD2, DDX58, IFIT3, and IFIT1." (PMID 28768533, 2017).